PRODH (proline dehydrogenase 1)
Diseases named in the same sentence as PRODH in open-access papers (continued):
Sharing a sentence is not in itself a finding about the gene and the disease.
hyperprolinemia type 1 (7 papers, 2011 to 2023). "Mutation in proline dehydrogenase (PRODH) in humans results in hyperprolinemia type I (HPI), while mutation in delta-1-pyrroline-5-carboxylate dehydrogenase (ALDH4A1/P5CDH) results in hyperprolinemia type II (HPII)." (PMID 32022684, 2020). "For example, our screened IEMs include short-chain Acyl CoA dehydrogenase deficiency (SCADD; associated with ACADS) and hyperprolinemia type I (HPI; associated with PRODH), both of which often do not yield symptomatic disease." (PMID 37443081, 2023). "A recent case control study reported microdeletions encompassing the PRODH and DGCR6 genes to be a strong risk factor for hyperprolinemia type 1 but not for autism spectrum disorder suggesting more emphasis on the other lesser known FAM230F and DGCR5 genes." (PMID 34938854, 2021).
pancreatic cancer (7 papers, 2017 to 2024). "PRODH expression has been previously reported to be dysregulated in several types of cancer, including colorectal, renal, mammary, lung and pancreatic carcinomas." (PMID 38255788, 2024). "To further explore how FTH1 is linked to the reprogramming of proline metabolism in pancreatic cancer cells, we measured the protein expression of proline metabolism-associated molecules, PYCR1 and PRODH, in control and shFTH1-infected SUIT-2 cells through Western blotting." (PMID 39294443, 2024). "Additionally, pancreatic cancer patients with elevated PRODH expression had a shorter median overall survival than those with lower PRODH expression, highlighting the potential prognostic value of these enzymes in pancreatic cancer." (PMID 39294443, 2024). "Moreover, pancreatic cancer patients with low PRODH, P4HA and PYCR1 expression had longer survival times than cancer patients with higher expression; in contrast, patients with low PRODH2 expression had shorter survival times than those with high PRODH2 expression." (PMID 36088469, 2022). "The interconversion among glutamine, proline, and collagen is mainly mediated by proline dehydrogenase 1 (PRODH1), which is necessary for pancreatic cancer cell growth." (PMID 36797531, 2023).
prostate carcinoma (7 papers, 2018 to 2024). A carcinoma that arises from epithelial cells of the prostate gland. "Findings from the MYC-inducible human Burkitt lymphoma model P493 and PC3 human prostate cancer cells affirm that MYC primarily suppresses POX/PRODH expression by up-regulating miR-23b." (PMID 38544804, 2024). "A substantial quantity of P5C generated by high expression of PRODH in prostate cancer cells induces an increase in ROS generation and a decrease in cytokines and ATP production, which results in the suppression of T cell function." (PMID 38023181, 2023). "In prostate cancer, lung, and pancreatic ductal adenocarcinoma, the expression of PRODH/POX was upregulated, but was downregulated in the human digestive tract and kidney tumors." (PMID 34577574, 2021). "In order to further validate our inferences, we also examined the expression of PRODH in human prostate cancer (PCa) and benign prostatic hyperplasia (BPH) tissues." (PMID 30545412, 2018). "Although the tumour-promoting or suppressing role of PRODH in tumour cells is highly context dependent, recent studies showed that prostate cancer cells suppressed T cell responses via the metabolite 1-pyrolline-5-carboxylate, a downstream product of proline catabolism by PRODH." (PMID 34637000, 2021). "However, a recent study indicated that PRODH can suppress T-cell infiltration in prostate cancer." (PMID 38023181, 2023).
psychosis (7 papers, 2012 to 2024). "For example, COMT and PRODH have been linked to both psychosis and ASD34,35." (PMID 33139857, 2020). "Because abnormalities in glutamatergic signaling are thought to be responsible for cognition and psychosis in the general population, we hypothesized that PRODH haplo-insufficiency may underlie some of the cognitive and psychotic features seen in 22q11DS." (PMID 26055684, 2015). "As a matter of fact, this region includes numerous genes involved in cognitive functions (i.e., COMT, PRODH, RTN4R, and DGCR8) and the patients show a higher risk for developing a psychotic disorder across their lifespan." (PMID 38392589, 2024). "The corresponding 22q11.2-haplotype analysis revealed an association between a specific “risk” haplotype, contained two “damaging” variants in PRODH and CLTCL1 genes, and psychosis." (PMID 30710087, 2019). "The PRODH gene is located on chromosome 22q11, a region related to psychotic disorders." (PMID 29694413, 2018). "The MLPA kit that we used (P250-A1) lacked probes in the candidate PRODH gene located in the proximal breakpoint which was found to be associated with psychotic disorders in 22q11.2DS." (PMID 23245648, 2012). "Although the latest research does not support the theory that high proline level is responsible for psychosis, it cannot be excluded that nullisomy of the PRODH gene has no clinical effect." (PMID 36980952, 2023).
22q11.2 deletion syndrome (6 papers, 2014 to 2025). 22q11.2 deletion syndrome (DS) is a chromosomal anomaly which causes a congenital malformation disorder whose common features include cardiac defects, palatal anomalies, facial dysmorphism, developmental delay and immune deficiency. "DGCR5, DGCR9, and PRODH in 22q11.21 have been reported to be associated with Digeorge Syndrome." (PMID 34079576, 2021). "For example, if the PRODH deletion in 22q11.2 deletion syndrome may lead to hyperexcitation, and the deletion of GABA receptor genes in Angelman syndrome may lead to hypoinhibition, an increased E/I ratio is observed in both." (PMID 40490701, 2025). "PRODH maps to the 22q11.2 region deleted in velocardiofacial syndrome (VCFS), a haploinsufficiency disorder that leads to a variety of physical and psychiatric problems, including SZ and ASD, and IFITM1 has been found to be differentially expressed in the brains of patients with SZ and ASD." (PMID 24736721, 2014). "With regards to the neurobehavioral features seen in 22q11.2 deletion syndrome, the roles of COMT (catechol-O-methyltransferase) and PRODH (proline dehydrogenase) have been investigated, given their relevance to dopaminergic and glutamatergic neurotransmission, respectively." (PMID 35046931, 2021).
colon cancer (6 papers, 2008 to 2020). "In the model of colon cancer cells with doxycycline regulated PRODH/POX expression activation of PRODH/POX significantly reduced COX-2 expression, PGE2 level and induced ROS generation leading to strong proapoptotic effect." (PMID 32710395, 2020).
non-small cell lung carcinoma (6 papers, 2020 to 2023). A group of at least three distinct histological types of lung cancer, including non-small cell squamous cell carcinoma, adenocarcinoma, and large cell carcinoma. "Recent research has highlighted the importance of PRODH in the progression of non-small cell lung cancer (NSCLC)." (PMID 38023181, 2023). "Interestingly, PRODH was also shown as capable of promoting tumor progression in non-small cell lung cancer (NSCLC) as part of a network involving a chromatin remodeler, the lymphoid-specific helicase (LSH)." (PMID 34291343, 2021).
glioma (5 papers, 2019 to 2024). A benign or malignant brain and spinal cord tumor that arises from glial cells (astrocytes, oligodendrocytes, ependymal cells). "The data from other non-glial neoplasms corroborates the inconclusive role of POX/PRODH in the studies we examined." (PMID 35454935, 2022). "Indeed, studies on non-glial neoplasms have come to the conclusion that POX/PRODH might play an ambiguous, context-dependent role depending on factors that are yet to be established." (PMID 38275897, 2024).
lung carcinoma (5 papers, 2020 to 2024). "This work focused on the role played by PRODH, a mitochondrial enzyme involved in proline metabolism and playing an important role in the induction of apoptosis and autophagy in lung cancer." (PMID 38255788, 2024). "In conclusion, the results described in this study suggest that PRODH plays a role in lung cancer tumorigenesis by inducing cellular senescence." (PMID 38255788, 2024). "To investigate PRODH expression in lung cancer, we performed immunohistochemical analyses on 148 lung cancer samples, of which 135 were NSCLCs and 13 were SCLCs." (PMID 38255788, 2024). "Thus, our data confirm these observations in lung cancer cell lines as well, providing support to the general role of PRODH in the induction of cellular senescence." (PMID 38255788, 2024). "To this aim, PRODH expression in lung cancer was characterized by immunohistochemistry; we tested the possible correlation between the expression of this protein and the expression of known lung cancer markers." (PMID 38255788, 2024). "In any case, although the conclusions drawn in this work are based on few cellular models, most cancer cell lines used apparently showed extreme sensitivity to PRODH overexpression in vitro, thus reinforcing the notion of an oncosuppressive role for this gene in lung cancer." (PMID 38255788, 2024). "Moreover, to elucidate the functions exerted by PRODH in lung cancer, we modulated its expression in ADC cell lines and performed a series of phenotypic assays." (PMID 38255788, 2024).
Anxiety (4 papers, 2014 to 2021). Intense feelings of nervousness, tension, or panic often arise in response to interpersonal stresses. "For example, PRODH variant has been linked to elevated prepulse inhibition and greater anxiety in adults from the general population, and elevated proline level has been associated with impaired brain function in 22q11DS." (PMID 33187471, 2020).
triple-negative breast carcinoma (4 papers, 2020 to 2024). An invasive breast carcinoma which is negative for expression of estrogen receptor (ER), progesterone receptor (PR), and human epidermal growth factor receptor 2 (HER2). "HDAC inhibitors, such as TSA/SAHA, have also been found to induce an increase in PRODH expression through AMPK activation in triple-negative breast cancer (TNBC) cells." (PMID 38023181, 2023). "PRODH/POX contributes to survival of triple negative breast cancer (TNBC) cells treated with HDAC inhibitors." (PMID 32500033, 2020). "However, a recent study shows that PRODH induced triple-negative breast cancer (TNBC) cell malignant phenotypes and overexpression of PRODH sensitized TNBC cells to clinical therapeutic drugs, including lipodox and Palbociclib." (PMID 39457440, 2024).
breast tumors (3 papers, 2018 to 2020). "The recent discovery that PRODH/POX in breast tumors is upregulated during metastatic reprogramming is of considerable interest and shows that the pattern of expression is linked to specific transitions." (PMID 28990419, 2019).
Burkitt lymphoma (3 papers, 2020 to 2024). A rare form of malignant mature B-cell non-Hodgkin lymphoma. "In Burkitt lymphoma, MYC suppressed POX/PRODH expression and increased P5CS and PYCR1, leading to reprogramming of proline and glutamine metabolism." (PMID 33465163, 2021). "In P-493 Burkitt’s lymphoma cells, MYC transcriptionally upregulates miR-23b* to decrease the translation of POX/PRODH, leading to the inhibition of proline catabolism." (PMID 32651356, 2020).
lung adenocarcinoma (3 papers, 2023 to 2024). A carcinoma that arises from the lung and is characterized by the presence of malignant glandular epithelial cells. "In conclusion, we provide evidence that PRODH affects both the 2D and 3D growth of lung adenocarcinoma cell lines by inducing cellular senescence." (PMID 38255788, 2024). "PRODH expression was found in the majority of lung adenocarcinomas (ADCs)." (PMID 38255788, 2024).
oral squamous cell carcinoma (3 papers, 2021 to 2024). "Similar results were presented in in vitro study, showing that Cx upregulates PRODH/POX in oral squamous cell carcinoma." (PMID 34577574, 2021). "In the model of oral squamous cell carcinoma, Tołoczko-Iwaniuk demonstrated that celecoxib, a well-known inhibitor of COX-2, increased levels of POX/PRODH and, as a result, led to apoptosis." (PMID 35454935, 2022). "Similarly, Tołoczko-Iwaniuk, studying oral squamous cell carcinoma, demonstrated that a COX-2 inhibitor, celecoxib, leads to apoptosis through increased levels of POX/PRODH." (PMID 38275897, 2024).
developmental delay (2 papers, 2023). "Humans with homozygous mutations in PRODH display elevated levels of L-Proline as well as multiple NDDs including developmental delay, ID, ASD, and SZ." (PMID 37794116, 2023).
endometrial adenocarcinoma (2 papers, 2021 to 2023). "An example is inhibition of collagen biosynthesis by betulin derivative contributing to PRODH/POX-dependent apoptosis in endometrial adenocarcinoma cells." (PMID 33818628, 2021).
epilepsy (2 papers, 2019 to 2020). A brain disorder characterized by episodes of abnormally increased neuronal discharge resulting in transient episodes of sensory or motor neurological dysfunction, or psychic dysfunction.
germ cell tumor (2 papers, 2021 to 2023). A benign or malignant, gonadal or extragonadal neoplasm that originates from germ cells. "Germ cell tumors with high expression of this HERV also show high expression of PRODH and forced differentiation of these tumor cells results in concomitant down-regulation of PRODH and ERVK-24." (PMID 33467098, 2021).
hepatocellular carcinoma (2 papers, 2013 to 2023). A malignant tumor that arises from hepatocytes. "Finally, we found that in the Mahlavu hepatocellular carcinoma cell line PRODH expression was diminished upon DOXO treatment." (PMID 23861960, 2013). "Finally, PRODH expression was analyzed in the Mahlavu hepatocellular carcinoma cell line after DOXO treatment." (PMID 23861960, 2013). "In Huh7.5 hepatoma cells, the expression of proteins synthesizing proline from P5C (PYCR1, PYCR2, PYCR3) prevails over proline-utilizing proteins (PRODH and PRODH2) and the coordinated action of PYCR3, PRODH, and PRODH2 proteins." (PMID 37189460, 2023).
liver cancer (2 papers, 2022 to 2024). An epithelial or non-epithelial malignant neoplasm that arises from the liver. "Some authors, attempting to summarize studies based on research in renal, rectal, stomach, and liver cancers, hypothesized that tumors need to down-regulate POX/PRODH activity in order to thrive." (PMID 35454935, 2022).
microcephaly (2 papers, 2014 to 2025). A congenital or acquired developmental disorder in which the circumference of the head is smaller than normal for the person's age and sex. "Participant 102 is a 28-month-old male with tall stature and microcephaly with a very small gain of the 22q11.21 region containing the PRODH gene encoding proline dehydrogenase." (PMID 25400949, 2014). "The monoallelic PRODH gain identified in a FISH‐ and MLPA‐negative patient (ID 69) who presented velopharyngeal insufficiency, short stature, psychomotor delay, swallowing difficulties, microcephaly, recurrent otitis media, and facial dysmorphism was considered an incidental finding." (PMID 41165438, 2025).
behavioral disorders (1 paper, 2017). "Despite the strong implication of PRODH in behavioral disorders, the exact mechanisms by which PRODH and altered proline metabolism contribute to these disorders are not well understood and their study would benefit from a genetically tractable model." (PMID 28331058, 2017). "Here, we establish a Drosophila model to study the role of PRODH in behavioral disorders." (PMID 28331058, 2017).
breast adenocarcinoma (1 paper, 2013).
cancer of kidney (1 paper, 2018). "In several cancer cells, as cancer of kidney or cancers of digestive tract, the expression of PRODH/POX is very low or not detected." (PMID 29681859, 2018).
cognitive decline (1 paper, 2012). "It is tempting to speculate that genes such as PIK4CA and SNAP29 that are deleted in our patient may be involved in the emergence of psychotic "positive symptoms" while others, such as PRODH and COMT that are not deleted, play a role in the cognitive decline process." (PMID 23245648, 2012).
colorectal adenocarcinoma (1 paper, 2024). The most common type of colorectal carcinoma. "Previous studies have shown that PRODH is linked to Complex II of the mitochondrial electron transport chain in mitochondrial inner membranes and its expression resulted in a dose-dependent down-regulation of Complexes I–IV of the ETC in human colorectal adenocarcinoma epithelial cells." (PMID 38480845, 2024).
colorectal tumor (1 paper, 2016). "Using the Tet-off system, the growth of xenograft colorectal tumor is suppressed by expressing PRODH in immune-deficient mice." (PMID 27391030, 2016).
embryonic carcinoma (1 paper, 2020). "Furthermore, the upstream LTR5_Hs is a validated enhancer of the PRODH gene in embryonic carcinoma cells." (PMID 33202765, 2020).
head and neck squamous cell carcinoma (1 paper, 2013). A squamous cell carcinoma that arises from any of the following anatomic sites: lip and oral cavity, nasal cavity, paranasal sinuses, pharynx, larynx, and salivary glands. "Three additional cell lines were instead used to explore PRODH responsiveness to endogenous p63: HaCat cells, derived from immortalized keratinocytes, and two cell lines derived from head and neck squamous cell carcinomas, namely JHU-029 and JHU-011." (PMID 23861960, 2013).
hydroxyprolinemia (1 paper, 2022). "Mary Efron showed no detectible difference in PRODH activity or proline metabolism in patients with hydroxyprolinemia and no deficiency of PRODH." (PMID 36818667, 2022).
myocardial infarction (1 paper, 2020). Gross necrosis of the myocardium, as a result of interruption of the blood supply to the area, as in coronary thrombosis. "First, through public database analysis and RT-qPCR and western blot analyses in a cardiomyocyte hypoxia model, we found that the expression of the proline-degrading enzyme PRODH was downregulated after myocardial infarction and hypoxia exposure." (PMID 33294127, 2020).
oral cancer (1 paper, 2020). "In the group of G2 tumours (Ki-67 40–70%), differences in the expression of examined proteins reached medial values: the mean value of PRODH/POX expression in oral cancer tissue was 55%, the mean value of PPARy—60% and mean value of HIF-1α—137%." (PMID 31935820, 2020). "It appears that celecoxib, which influences the PRODH/POX pathway, may be a promising therapeutic compound in oral cancer treatment." (PMID 31935820, 2020). "The results of our study demonstrated lower expression of PRODH/POX and PPARγ and higher expression of HIF-1α in oral cancer tissue in comparison to normal tissue in all study participants, although the obtained values differed significantly between individual patients." (PMID 31935820, 2020).